CDK4 (cyclin dependent kinase 4)
Diseases named in the same sentence as CDK4 in open-access papers (continued):
Sharing a sentence is not in itself a finding about the gene and the disease.
breast cancer (continued). "For these patients, S6K1 blockade using upstream mTOR inhibitor could increase the sensitivity of breast cancer to CDK4/6 inhibitor." (PMID 36042494, 2022). "Combination therapies might therefore elevate the response rates in FGFR2amp tumours, as proposed for FGFRi–CDK4/6i combination therapy in patients with breast cancer with FGFR2 and CCND1 amplifications." (PMID 35948633, 2022). "Cyclin D1 and CDK4 play particularly important roles in mammary gland biology and breast cancer." (PMID 35248122, 2022). "Importantly, Cyclin E-CDK2 complexes drive cell-cycle progression (S-phase entry) and the activation of CDK2 represents one of the mechanisms of CDK4/6i resistance in breast cancer." (PMID 35546399, 2022). "79% of patients in the trial received prior CDK4/6i for advanced breast cancer." (PMID 36229710, 2022). "CDK2 and CDK4 reduction arrest the G1 cell-cycle in MCF-7 human breast cancer cells." (PMID 35216267, 2022). "The increase in CDK4 could be a potential therapeutic target since selective inhibitors of CDK4/6 are now available and already widely used in the management of breast cancers." (PMID 35406448, 2022). "However, CDK4/6I-resistant breast cancer cells demonstrated upregulation of IFN-ɑ and IFN-β activity in immune-related signaling pathways." (PMID 36358806, 2022). "Thus, alpelisib has been confirmed as an important backup option for patients with CDK4/6 inhibitor‐resistant breast cancer." (PMID 38089455, 2022). "The FDA recently approved the dual CDK4/6 inhibitors Palbociclib, robocalled, and abaculi in combination with other medications for the treatment of hormone receptor positive (HR+) advanced or metastatic breast cancer as well as other breast cancer subtypes." (PMID 36299580, 2022). "For example, cyclin D1 is required for mammary epithelial proliferation in pregnancy, and knockout of either cyclin D1 or CDK4 prevents the development of mammary carcinomas from luminal epithelial cells driven by particular oncogenes, such as Neu or Ras, in mice." (PMID 35248122, 2022). "The overexpression of CDK4/6 is usually seen in luminal types of breast cancer." (PMID 35530846, 2022). "In breast cancer we identified rearrangement hot spots near CCND1 and in glioma near CDK4 and MDM2 and could directly associate this with increased expression." (PMID 34891161, 2021). "For example, two neo-adjuvant clinical trials, including palbociclib (CDK4/6i) plus endocrine therapy, showed that increased IFN/STAT1 signaling in ER+ breast cancers were associated with elevated immune checkpoint levels, endocrine resistance, and poor outcome." (PMID 33807608, 2021). "To clarify this hypothesis, we investigated estrogen sensitivity in the CDK4/6 inhibitor-sensitive or -resistant breast cancer cells in this study." (PMID 32860163, 2021). "In addition, a recent study reported that p21 levels were proportional to CDK4/6 inhibitor sensitivity and had the potential as a monitoring marker for ribociclib, an FDA-approved CDK4/6 inhibitor in late-stage breast cancer." (PMID 33925607, 2021). "Additionally, there are many targeted small molecule inhibitors under clinical trials for the treatment of breast cancer, such as the CDK4/6 inhibitor palbociclib, the PI3K/Akt/mTOR pathway inhibitor pictilisib, the HDAC inhibitor CUDC-101." (PMID 33986665, 2021). "The CDK4/6 inhibitor palbociclib can further be used in combination with anti-estrogens and this parallel inhibition of the cell cycle and the ERα-signaling is an efficient treatment strategy for certain subgroups of breast cancer patients." (PMID 34172801, 2021). "For example, ribociclib targeting CDK4/6 is used in breast cancer therapy." (PMID 34650921, 2021). "As a result of these studies, several therapies that combine anti-estrogens that degrade ERα with PI3K/AKT/mTOR inhibitors targeting growth factor signaling or CDK4/6 inhibitors targeting cell cycle machinery are used clinically to treat recurrent ERα+ breast cancers." (PMID 33498407, 2021).
breast cancer (continued). "The introduction of CDK4/6 inhibitors (CDK4/6i) in combination with endocrine therapy (ET) has revolutionized the treatment landscape for patients with estrogen receptor-positive (ER+) advanced breast cancer (ABC) and has become the new standard treatment." (PMID 34771560, 2021). "Transcriptional profiling on a panel of seven breast cancer cell lines showed indeed a characteristic signature of significantly downregulated genes for abemaciclib that goes beyond the profile of the target protein CDK4/6 kinase activity." (PMID 34785661, 2021). "Therefore, in this study, we examined the antitumor effects of the CDK4/6 inhibitor abemaciclib and ABT‐263 using MDA‐MB‐231 and MCF‐7 human breast cancer cell lines and investigated the underlying mechanisms." (PMID 34761877, 2021). "Fortunately, substantial progress has been made after major advances in our understanding of the biology of ER+/HER2– breast cancer in the past 20 years, such as the development of CDK4/6 inhibitors, mTOR inhibitors, PI3Kα inhibitors and histone deacetylase inhibitors." (PMID 33676449, 2021). "Collectively, miR126 upregulation sensitized breast cancer cells to CDK4/6 inhibition." (PMID 34439268, 2021). "We may infer that FMNL2 decreased the nuclear localization of p27 and the protein stability of p27, thus promoting CDK4/CyclinD1 kinase activity and cell proliferation of human breast cancer cells." (PMID 34193109, 2021). "The significance of the CDK4/6-DUB3 axis in regulating breast cancer metastasis has been confirmed by another study, demonstrating that the inhibitor of DUB3, WP1130, suppresses DUB3-mediated Snail1 stabilization and that IL-6 stabilizes Snail1 by activating DUB3." (PMID 34454495, 2021). "Furthermore, 9-cis RA decreased cyclin D1 and D3 expression levels as well as the expression and activity of CDK2 and CDK4 in breast cancer cells." (PMID 34444715, 2021). "Moreover, this L30I40 synergistic anti-breast cancer effect by the combination was mediated by reducing the CDK4/6/Rb pathway to induce stringent growth arrest in the G1 cell cycle, as well as induced apoptosis." (PMID 33925607, 2021). "Thus, the beneficial effects on survival in breast cancer reported with aromatase inhibitors and the CDK4/6 inhibitors palbociclib and ribociclib is likely to also be mediated by their respective immune effects." (PMID 34078406, 2021). "Moreover, CDK4/6 inhibitors are currently widely used for the treatment of breast cancer, and their therapeutic value in this disease context has attracted significant attention." (PMID 34395284, 2021). "However, studies have demonstrated that the degree of cell cycle inhibition of CDK4/6i in PDAC is significantly more modest compared to the response observed in breast cancer models." (PMID 34828525, 2021). "This suggests the therapeutic utility of chemical inhibitors of CDK4/6 in ERα+ breast cancers." (PMID 33498407, 2021). "Overall, these observations suggest that inhibition of p27 specific phosphorylations, cooperating with CDK4 inhibitors, could be a strategy to target CDK4-dependent tumors such as estrogen receptor–positive breast cancers." (PMID 34571903, 2021). "It should be thus postulated that certain miRNAs may be involved in both CDK4/6 inhibitor and endocrine therapy resistance in luminal breast cancer." (PMID 34439268, 2021). "This suggests that functional ER could also be important for the efficacy of CDK4/6 inhibitors in ER+ breast cancer." (PMID 33531464, 2021). "However, ER + advanced breast cancer patients with intrinsic resistance to endocrine therapy and treated with combined CDK4/6i and endocrine therapy whose tumors expressed low AURKA exhibited significantly shorter PFS." (PMID 33398005, 2021). "In all, our data indicated that FMNL2 may promote CDK4/CyclinD1 kinase activity and cell proliferation through inhibition of p27 nuclear localization and p27 protein stability in human breast cancer cells." (PMID 34193109, 2021).
breast cancer (continued). "For patients with ET-resistant breast cancer cells, the combined use of ET and cyclin-dependent kinase 4/6 (CDK4/6) inhibitors with adjuvant therapy may improve survival." (PMID 33672204, 2021). "We then tested this hypothesis in CDK4/6i resistant breast cancer cell lines, which was obtained by continuously being treated with CDK4/6i." (PMID 34508104, 2021). "However, acquired resistance to CDK4/6 inhibitors, as observed during breast cancer treatment, is expected and the mechanism involves amplification of CDK6 or loss of function of Rb165,66." (PMID 34893606, 2021). "Likewise, elevated CCND1 expression (encoding the CDK4/6 binding partner, Cyclin D1) is associated with lower expression of MHC I genes in breast cancer patients." (PMID 34025662, 2021). "The goal of this study was to investigate whether inhibition of WEE1 is an effective therapy for breast cancer cells that have progressed on endocrine therapies and are intrinsically resistant to CDK4/6 inhibitors." (PMID 34277427, 2021). "The CDK4/6 inhibitors, palbociclib (PD-0332991), ribociclib, and abemaciclib, in combination with endocrine therapy are frequently used to treat recurrent ERα+ breast cancer and have improved progression free survival (PFS)." (PMID 33498407, 2021). "In addition, CDK2 and CDK4 are hypomethylated but are less frequently mutated: CDK2 (2 cases 0.19%) and CDK2 (1 case 0.10%) in breast cancer." (PMID 34421361, 2021). "In this review, it was noted that three in vitro studies (4.4%) reported that carvacrol decreased CDK4 protein expression in human tongue squamous cell carcinoma (Tca-8113 cells) and in breast cancer (MCF-7 cells) and only one (1.4%) reported a decrease in CDK6 in MCF-7 cells." (PMID 34305611, 2021). "Based on preclinical studies suggesting that up-regulation of the PI3K-AKT-mTOR signaling pathway causes acquired resistance to CDK4/6 inhibitors, the mTOR inhibitor everolimus and PI3K inhibitor alpelisib have been clinically used to manage CDK4/6 inhibitor-resistant breast cancer." (PMID 32860163, 2021). "Thus, CDK4/6 inhibition is a potential candidate to combine with ICB in patients with HR+ breast cancer." (PMID 34135901, 2021). "In addition, CDK4/6i treatment led to RB1 protein reduction in a time-dependent manner in multiple breast cancer cell lines." (PMID 34508104, 2021). "One of the pressing clinical questions is whether an optimal combination therapy in conjunction with CDK4/6 inhibition exists and if that will benefit the majority of breast cancer patients." (PMID 34944934, 2021). "Utilizing this model in ER+ breast cancer patients could help to identify which patients are likely to favorably respond to CDK4/6 inhibition and which patients will probably have intrinsic resistance, and therefore should take a different course of treatment." (PMID 34830174, 2021). "In multiple ER+ breast cancer cell lines, the WEE1 inhibitor AZD1775 (MK1775), which works to decrease WEE1 activity at the G2/M checkpoint, has been shown to increase sensitivity in cells resistant to CDK4/6 inhibitors and cause cell death." (PMID 34830174, 2021). "Understanding the relationship between the HER2-Akt-mTOR pathway, glycolysis, and CDK4/6 may pave the way for improved therapies to treat HER2-positive breast cancer and overcome drug resistance." (PMID 34208071, 2021). "However, recent analyses revealed that treatments with CDK4/6 inhibitors and endocrine therapy provided progression-free survival benefits in addition to overall survival benefits in patients with advanced breast cancer compared with endocrine therapy alone." (PMID 32860163, 2021).
breast cancer (continued). "Moreover, loss of endogenous negative regulators of CDK4/6, CDKN2A,and CDKN2C, results in hyperactivity of CDK4/6 in ERα+ breast cancers." (PMID 33498407, 2021). "Since autophagy is a known mechanism of ER+ tumor resistance to CDK4/6 inhibitors, future studies should focus on repeating this experiment with models of this subtype of breast cancer to confirm that this mechanism of overcoming resistance is also valid in the ER+ population." (PMID 34830174, 2021). "CDK4 was found to be amplified in 14% of luminal A and 25% of luminal B breast cancer patients." (PMID 34729098, 2021). "Detailed mechanisms of resistance to CDK4/6i in breast cancer have been the subject of several recent reviews, but as a brief summary, current evidence largely points towards a unifying theme of eliminating hypophosphorylated pRb to allow progression through the G1 cell cycle checkpoint." (PMID 34804982, 2021). "Combinations of CDK4/6i and endocrine therapy are standard of care in advanced ER+ breast cancer." (PMID 32940689, 2021). "Here, we demonstrate that a triple combination of the AKTi, CDK4/6i, and fulvestrant is required to durably impair growth and prevent progression in ER+ breast cancer cell lines and tumor xenografts resistant to combined therapy with fulvestrant and CDK4/6i or fulvestrant alone." (PMID 34433817, 2021). "Therefore, we assessed the effects of abemaciclib (the first FDA-approved CDK4 inhibitor for breast cancer treatment) on the HCC cell lines Hep3B and Huh7." (PMID 33686022, 2021). "Together, these data suggest that breast cancer cells resistant to the combination of CDK4/6i and endocrine therapy will rapidly progress on fulvestrant and AKTi, but will benefit from the addition of AKTi to the standard combination of CDK4/6i and fulvestrant." (PMID 34433817, 2021). "Ongoing phase I trials are investigating the efficacy of the CDK7 inhibitors SY-1365 and CT-7001 combined with fulvestrant in patients with solid tumors, including ER+/HER2− breast cancer patients who progressed on CDK4/6i-based therapy (NCT03134638, and NCT03363893)." (PMID 34771560, 2021). "Next, we investigated whether MCM3 expression affects response to combined CDK4/6i and endocrine therapy in ER+ breast cancer cell lines." (PMID 33398005, 2021). "The addition of CDK4/6i such as palbociclib or ribociclib to endocrine therapy almost doubles progression free survival compared to aromatase inhibitors alone in metastatic oestrogen receptor positive breast cancer." (PMID 34944961, 2021). "In breast cancer (89 respondents), the most affected treatment was everolimus, which was estimated to be permanently stopped or delayed in more than 10% of patients by 15%, followed by CDK4/6 inhibitors by 8.9% and alpelisib by 6.7% of respondents." (PMID 33529077, 2021). "In this study, we use real-world evidence to assess the use and effectiveness of everolimus exemestane as first-line, second-line, or third-line therapy following prior endocrine therapy alone vs endocrine therapy + CDK4/6i in patients with metastatic hormone-positive HER2− breast cancer." (PMID 33514405, 2021). "CDK4/6 inhibition has been mainly targeted towards the treatment of breast cancers." (PMID 34359832, 2021). "Indeed, several preclinical studies have shown synergistic inhibition of Rb and mTORC1 by combining PI3Ki and CDK4/6i in breast cancer cell models resistant to CDK4/6i single agent." (PMID 34771560, 2021). "Importantly, our MCF-7-derived breast cancer cell line resistant to the combination of fulvestrant and CDK4/6i also expressed higher p-AKT levels compared to the respective parental cell line." (PMID 34433817, 2021). "Furthermore, we show that CDK4/6i treatment can alter the protein levels of RB1 and CDK6 to confer breast cancer cells with acquisition of CDK4/6i resistance." (PMID 34508104, 2021).
breast cancer (continued). "In addition, four proteins in the cancer cell growth pathway are targeted for therapeutic purposes in breast cancer, including cyclin-dependent kinase 4 and 6 (CDK4/6), poly (ADP-ribose) polymerase (PARP) and phosphoinositide-3-kinase (PI3K)." (PMID 34361688, 2021). "MiR‐124 targets CDK4 mRNA and inhibits protein expression in breast cancer cells." (PMID 34724356, 2021). "Interestingly, it has been demonstrated that the increased CDK6 expression observed in CDK4/6i-resistant breast cancer cell models is dependent on the suppression of the TGF-β pathway by the miR-432-5p expression." (PMID 34771560, 2021). "Aberrant CDK4 amplification in malignant tissues has been reported to be involved in the development and progression of various cancers including liposarcoma, glioblastomas, breast cancer, ovarian cancer, and melanoma through the cyclin D1–CDK4/6–Rb pathway." (PMID 33995474, 2021). "Furthermore, no cassette of markers has proved important in patients with breast cancer treated with CDK4/6 inhibitors." (PMID 33427211, 2021). "The CDK4/6 inhibitor class of drugs has been found to improve survival in metastatic ER+ breast cancer patients and is being evaluated as adjuvant treatment for early breast cancer patients." (PMID 34642313, 2021). "Inhibition of CDK4/6 slows the cell cycle and induces senescence in breast cancer cells." (PMID 34761877, 2021). "Furthermore, it is reported that the amplification of cyclin D1 and CDK4 is particularly high in HER2+/HR+ breast cancer (58 and 25%, respectively)." (PMID 34977029, 2021). "Thus, abemaciclib is theoretically the best equipped CDK4/6 inhibitor for use in breast cancer patients with brain metastases, which is further being investigated in an ongoing trial (NCT02308020)." (PMID 34830174, 2021). "Finally, BYLieve supports the notion that the PIK3Ca inhibitor alpelisib is a reasonable treatment option in patients with PIK3Ca mutant luminal breast cancer progressing on CDK4/6-inhibitor therapy." (PMID 33520003, 2021). "The third CDK4/6 inhibitor that received FDA approval in metastatic breast cancer was abemaciclib and is currently under investigation as an adjuvant treatment in patients with high-risk node-positive early breast cancer in MonarchE trial." (PMID 34198899, 2021). "However, our knowledge of how breast cancer cells develop resistance to CDK4/6 inhibitors is incomplete." (PMID 34277427, 2021). "Addressing this hypothesis experimentally would be of high interest and would further shed light on the effects of CDK4/6-targeted therapy in breast cancer." (PMID 34944934, 2021). "Finally, high phospho-AKT levels in metastasis of breast cancer patients treated with a combination of CDK4/6i and endocrine therapy correlates with shorter progression-free survival." (PMID 34433817, 2021). "CDK4/6 inhibitors have shown significant antitumor activity in advanced HR+/HER2− breast cancer." (PMID 34638325, 2021). "Available agents such as CDK4/6 inhibitors and oral SERDs, which have demonstrable clinical activity in advanced breast cancer, may overcome resistance to standard endocrine therapy that enables dormant tumors to emerge and spread." (PMID 35223447, 2021). "In addition, suppression of the miR106b cluster upon CDK4/6 inhibition was confirmed in breast cancer explants sensitive to CDK4/6 inhibitors." (PMID 34439268, 2021). "Genetic alterations in the Ras–ERK pathway and Hippo pathways may contribute to CDK4/6i resistance in prostate and breast cancer, respectively." (PMID 33809714, 2021). "Cyclin D1, a well-known oncogene, is upregulated in up to 50% of breast cancers, which promotes G1–S cell cycle progression by forming a complex with cyclin dependent kinases 4/6 (CDK4/6), leading to the Rb phosphorylation and dissociation of transcription factor E2F from the pRb-E2F complex." (PMID 33824311, 2021).